VWF (von Willebrand factor)
Diseases named in the same sentence as VWF in open-access papers (continued):
Sharing a sentence is not in itself a finding about the gene and the disease.
COVID-19 (continued). "Fibrinogen and vWF antigen levels are significantly higher in patients with COVID-19." (PMID 36013974, 2022). "VWF is stored in the Weibel-Palade bodies of the endothelium, and it is likely that MC-derived histamine, one of the most potent Weibel-Palade bodies secretagogues, stimulates its release in the COVID-19 setting." (PMID 36225927, 2022). "Overall, we observed increased circulating levels of VWF:Ag and VWF:RCo, which were however higher in the COVID-19 group than in the non-COVID-19 group with a statistically significant difference reached for the VWF:Ag levels (mean [SD], 275.39 [184.97]% p = 0.041)." (PMID 36704480, 2022). "We observed a negative correlation of cfDNA with the ADAMTS13:VWF ratio, a marker associated with COVID-19 severity and severe AKI, along with a positive correlation with LDH, ferritin, and haptoglobin, suggesting a picture of a secondary TMA." (PMID 35497096, 2022). "Additionally, we also measured VWF concentrations in 159 COVID-19 patients and found they were significantly higher (p-value = 0.02868) in the ICU patients." (PMID 35634344, 2022). "Moreover, a decrease ADAMTS13, which ensure vWF hemostatic function, has been reported in severe forms of COVID-19." (PMID 36519165, 2022). "C3a and C5a bind to the anaphylatoxin receptors: C3aR, C5aR1, and C5aR2 and C5a is also able to activate endothelial cells in COVID-19 patients leading to von Willebrand Factor (vWF) and p-selectin exposure on the endothelial lining thereby contributing to the thrombotic phenotype." (PMID 35350780, 2022). "Fibrinogen, D-dimer, factor VIII, von Willebrand factor (vWF), and neutrophil extracellular traps (NETs) were greatly increased in COVID-19 model experiment and patients; these abnormal coagulation parameters indicating COVID-19 patients are in a hypercoagulable state." (PMID 36341356, 2022). "Although some platelet adhesion to the extruded VWF was observed over the subsequent 15 minutes for the channels where healthy plasma was added, this effect was markedly enhanced in those channels with added COVID-19 plasma." (PMID 35309299, 2022). "Thus, the analysis of the vWF/ADAMTS-13 ratio makes it possible to predict the course of COVID-19 when a patient is admitted to a hospital and can also be a useful tool for monitoring the severity of the disease." (PMID 35887770, 2022). "So, we speculated that the coagulation factors, especially factor VIII and VWF, can be increased in COVID-19 patients and can be related to thromboembolic manifestations exacerbating the condition in these patients." (PMID 35996516, 2022). "Nevertheless, an investigation measured total levels of von Willebrand factor (vWF) and vWF binding to platelet glycoprotein complex (GpIb-IX-V) in patients with COVID-19 from an intensive care unit, and both forms of the vWF were markedly increased in these patients." (PMID 35453794, 2022). "In adult non-pregnant patients with COVID-19, elevated VWF/ADAMTS-13 ratios were found associated with disease severity, being highest in those with worse illness or in non-survivors." (PMID 35189860, 2022). "Additionally, the variation of VWF and Factor VIII levels by ABO group with higher levels in these individuals contributes to risk of thromboembolic disease and severe COVID-19." (PMID 36013335, 2022). "For example, association with VWF and Factor VIII may indicate ABO affects COVID-19 through regulation of thrombosis, as patients with severe COVID-19 can have thromboembolic complications as part of a hyper-inflammatory state." (PMID 34001247, 2021). "However, COVID-19 (+) patients demonstrated significantly higher VWF:AG and CBA levels compared to COVID-19 (−) patients (p < 0.0001)." (PMID 35087853, 2021). "Additionally, vWF (a marker of endothelial injury and NETosis) was found to be increased in COVID-19 lungs compared to the normal reference range." (PMID 33499234, 2021). "In our study, VWF antigen levels were elevated both in patients with cirrhosis and COVID-19." (PMID 34945736, 2021).
COVID-19 (continued). "Consistent with this hypothesis are the observations that microangiopathy in the lung is highly prevalent among COVID-19 patients with CAC, and that age-associated increase, specifically in cellular expression of VWF, is observed in lung microvasculature." (PMID 34575297, 2021). "Consistent with this hypothesis, some studies have indicated that COVID-19 patients with Blood Group O (25% lower VWF levels than other blood groups) are significantly underrepresented in thrombogenic complications." (PMID 34575297, 2021). "Other groups have also shown marked elevations of vWF in patients with COVID-19." (PMID 34208470, 2021). "The VWF/ADAMTS-13 fraction may be a helpful tool to monitor COVID-19 patients throughout hospitalization." (PMID 34573989, 2021). "Both von Willebrand factor antigen (vWF:Ag) and von Willebrand factor ristocetin cofactor activities (vWF:RCo) were significantly higher in COVID-19 patients independently from their platelet count on admission compared to healthy subjects (p < 0.001) (data not shown)." (PMID 34940584, 2021). "Additionally, it is noteworthy that elevated VWF levels has been reported only in COVID-19 positive pneumonia patients." (PMID 34575297, 2021). "In line with this, numerous markers of endothelial injury, such as vWF and PAI-1, are particularly high in patients with COVID-19 who are admitted to the intensive care unit, which indicates that the levels of vWF and PAI-1 are highly correlated with COVID-19 severity." (PMID 34253862, 2021). "Likewise, in patients with severe COVID-19, plasma levels of vWf antigen are increased, while ADAMTS13 activity is normal or diminished." (PMID 33578631, 2021). "Additionally, the VWFpp/VWF:Ag ratio dropped as VWF clearance was reduced and this is thought to lead to the elevated plasma VWF:Ag levels seen in severe COVID-19." (PMID 33801921, 2021). "Since COVID-19 induces, in some patients, a thrombotic and microvascular injury syndrome, here, we have explored if placentas from women with COVID-19 exhibit an altered expression of vWf, claudin-5 and VE-cadherin in the decidua and chorionic villi." (PMID 33578631, 2021). "This may be a reflection of the fact that the massive inflammatory response seen in patients with COVID-19 has a greater impact on fibrinogen, von Willebrand Factor (vWF), and platelet levels, and less of an impact on coagulation factors." (PMID 33530346, 2021). "In addition to these effects, aldosterone stimulates the release of vWF from endothelial cells, enhancing leukocyte adherence, platelet adhesion and the formation of microthrombi, which are frequently reported in COVID-19 patients." (PMID 34594302, 2021). "However, VWF:AG levels exceed the reference range (0.5–2 U/mL) and VWF collagen binding activity is significantly increased in COVID-19 (+) patients." (PMID 35087853, 2021). "During the progression of the various stages of the COVID-19, markers of viral replication, as well as VWF and fibrinogen depletion with increased D-dimer levels and dysregulated P-selectin levels, followed by a cytokine storm, are likely to be indicative of a poor prognosis." (PMID 34328172, 2021). "The reduced risk of COVID-19 induced coagulopathy, due to the lower level of FVIII/VWF in O BG patients, may be another hypothesis that could explain the positive clinical course." (PMID 32950044, 2021). "Since endothelial inflammation and injuries are often observed in COVID-199, an impairment in VWF function because of an abnormal quality, abnormal local circumstance, or abnormal quantity of VWF might occur in COVID-19." (PMID 33664450, 2021). "In COVID-19, EV-TF activity was positively correlated with D-dimer, prothrombin time, and von Willebrand factor levels, indicating a link between TF-positive EVs, coagulation, and endothelial activation, which may contribute to thrombosis in COVID-19 patients." (PMID 34977191, 2021).
COVID-19 (continued). "Another factor that may also contribute to elevated levels of VWF in COVID-19 patients is development of hypoxic conditions." (PMID 34575297, 2021). "Coagulation factor VIII, von-Willebrand-factor (vWF), and angiopoietin 2 (Ang-2), which are stored in the Weibel-Palade bodies of endothelial cells and are released upon cell injury, are increased in COVID-19." (PMID 33604758, 2021). "Correlation of Angpt-2, P selectin, and vWF levels in our work and that of others suggests that Weibel-Palade body extrusion may be a common manifestation of COVID-19 endothelial cell injury." (PMID 34506304, 2021). "Similarly, Type I VWD patients with significantly lower VWF levels are also underrepresented in groups of COVID-19 patients with thrombogenic consequences." (PMID 34575297, 2021). "Furthermore, increased levels of fibrinogen, factor VIII, and VWF were observed in severely ill COVID-19 patients admitted to the ICU." (PMID 34769508, 2021). "Elevated levels of both VWF antigen and VWF activity were detected in the plasma of COVID-19 patients (with the higher values being observed among patients requiring intensive care), corroborating the previous observations of endothelial cell activation elicited by SARS-CoV-2 infection." (PMID 34977191, 2021). "Since vWF, FVIII, t-PA-1 and P-selectin are directly linked to coagulopathy and endotheliopathy, two main features of COVID-19, one may consider them as biomarkers for the disease." (PMID 33562030, 2021). "Clinical observations may induce to hypothesize that in COVID-19 patients the measurement of D-dimer, fibrinogen, VWF, and the platelet activation marker P-selectin may help clinicians in deciding treatment strategy on the basis of correct clinical diagnosis." (PMID 34948438, 2021). "We evaluated the impact of the VWF/ADAMTS-13 fraction on COVID-19 severity and prognosis." (PMID 34573989, 2021). "This suggests that synergistic effects of hypoxia with other COVID-19 related conditions might be responsible for increase in VWF levels during the disease progression." (PMID 34575297, 2021). "A cytokine storm in severely ill COVID-19 patients is another possible mechanism, because it suppresses the anticoagulant pathways and releases the von Willebrand factor, which might lead to thrombosis in these patients." (PMID 34573160, 2021). "Clinical features in patients with severe COVID-19 include increases in D-dimers and fibrin product degradation as well as elevations in von Willebrand factor and soluble P-selectin, suggesting the existence of endotheliopathy along with platelet activation in COVID-19-associated coagulopathy." (PMID 33841442, 2021). "Interestingly, the vWF/ADAMTS13 axis is directly investigated in the context of COVID-19-related VTE." (PMID 34564316, 2021). "Markers of coagulation disruption in COVID-19 currently under investigation include D-dimer levels, platelet count, Von Willebrand Factor (VWF), Factor VIII, thromboelastography (TEG), lupus anticoagulant (LAC), antiphospholipid antibodies (APLs), and fibrinogen." (PMID 33378321, 2021). "Microthrombosis in COVID-19 has been observed in all postmortem lung examinations and could be explained, at least in part, by the large von Willebrand factor (VWF) released following endothelial activation." (PMID 34722585, 2021). "Interestingly, other markers of endothelial coagulopathy were also significantly increased in COVID-19 patients, including VWF and its collagen-binding activity (p < 0.0001)." (PMID 34571942, 2021). "Consistent with this, lower platelet counts were observed in some COVID-19 patients, which could be due to hyperactivation of platelets and aggregate formation following platelet interaction with VWF." (PMID 34575297, 2021). "Many studies reported that coagulopathy associated with COVID-19 is characterized by thrombocytopenia, prolongation of the prothrombin time, high levels of D-dimer, and elevated levels of fibrinogen, factor VIII, and von Willebrand factor." (PMID 34153056, 2021).
COVID-19 (continued). "Raised levels of vWF are associated with acute respiratory distress syndrome and sepsis, and correlate independently to mortality, with evidence that the vWF axis is involved in delayed cerebral ischemia (DCI) secondary to aneurysmal subarachnoid hemorrhage (SAH) as well as COVID-19." (PMID 34208470, 2021). "Our findings verified earlier reports on the correlation between the VWF level and the severity of COVID-1951 by directly observing the increased concentration of platelet aggregates with its positive link to the severity of COVID-19." (PMID 34887400, 2021). "As smoking can increase the level of VWF and decrease the level of thrombomodulin, there could be a correlation between smoking and stroke occurrence in COVID-19 patients." (PMID 32486196, 2020). "Consistent with this hypothesis, other clinical manifestations of COVID-19 include cardiac injury and hypercoagulability as measured by an increased in D dimer and Von Willebrand factor (VWF) levels." (PMID 32660065, 2020). "Recent reports show elevated levels of VWF in COVID-19 patients (more than 565%)." (PMID 33228225, 2020). "However, during influenza infection, the levels of vWF antigen (123 to 211%) are lower when compared with COVID-19 patients." (PMID 33193350, 2020). "In this context, elevated circulating levels of VWF and FVIII have been demonstrated in patients with severe COVID-19 pneumonia, and this may indirectly link ABO blood groups with susceptibility to COVID-19." (PMID 38624655, 2020). "Additionally, two independent teams found that COVID-19 patients in ICU had markedly elevated levels of the von Willebrand factor, further supporting Levi M’s opinion." (PMID 32860672, 2020). "This complement activation leads to enhanced production of endothelial-production of cytokines, such as IL-1, IL-8, RANTES, IL-6, and MCP-1, and up-regulates crucial endothelial adhesion molecules, such as P-selectin and VWF, which further helps to develop thrombin formation in COVID-19 patients." (PMID 33228225, 2020). "Complement is another potential enhancer of thrombosis, the membrane attack complex C5b-9 being increased in COVID-19–infected patients, in parallel with other endothelial activation markers such as von Willebrand factor, tissue plasminogen activator, and plasminogen activator inhibitor-1." (PMID 33488398, 2020). "Besides VWF, acute inflammation characterized by elevated acute-phase proteins and cytokines has been suggested to play a role in the development of thrombosis in COVID-19 patients." (PMID 40224277, 2025). "Additionally, vWF levels were significantly higher in COVID-19 patients with unfavorable outcomes." (PMID 40283058, 2025). "Moreover, endothelial senescent cells are known to over-express substances such as plasminogen activator inhibitor and von Willebrand factor favoring a thrombogenic environment and clotting, which is one of the main features of both acute and persistent COVID-19." (PMID 39012668, 2024). "In addition, mictrothrombi rich in platelets and vWF were more common in COVID-19 patients." (PMID 39795908, 2024). "vWF and vWF-mediated signaling pathways contribute to coagulation, platelet activation, adhesion, and endothelial activation, making them attractive therapeutic targets for various thrombotic and infectious diseases, including stroke, thrombotic thrombocytopenic purpura, sepsis, and COVID-19." (PMID 38921594, 2024). "•VWF seems to contribute to thrombosis in COVID-19 and may be a therapeutic target." (PMID 37333991, 2023). "Plasma vWF antigen (vWF: Ag), high molecular weight multimers, and propeptide levels of vWF (vWFpp) are established markers of endothelial injury, markedly elevated during COVID-19 and may be crucial in endotheliitis and pulmonary microvascular occlusion in the pathogenesis of COVID-19." (PMID 36622519, 2023).
COVID-19 (continued). "However, to the best of our knowledge, ours is the first study assessing the potential contribution of a set of single nucleotide polymorphisms in the vWF and ADAMTS13 genes, key factors in the background of CAC, to increased thrombotic risk among COVID-19 patients." (PMID 36980889, 2023). "Markers of endothelial injury such as von Willebrand’s factor (VWF) and its cleaving protein, a disintegrin and metalloproteinase with thrombospondin type 1 motif, member 13 (ADAMTS13), also known as von Willebrand factor-cleaving protease (VWFCP), are also implicated in COVID-19 disease severity." (PMID 37987325, 2023). "The study reports that sP-Sel, VWF, and D-dimer were increased in individuals with COVID-19 pulmonary disease and correlated with proinflammatory cytokines and chemokines, suggesting that COVID-19 is a vascular disease which involves endothelial injury in the context of an inflammatory state." (PMID 36947108, 2023). "Endotheliopathy is marked by an increased level of plasma von Willebrand factor (VWF), E-selectin, plasminogen activator inhibitor-1 (PAI-1), soluble thrombomodulin (sTM), and syndecan-1, which is strongly associated with a poor outcome in patients with severe COVID-19." (PMID 36675479, 2023). "This indicates that vWF may serve as a potential target in COVID-19 pathogenesis." (PMID 36982738, 2023). "In addition, thrombotic events occur in COVID-19 patients, which is known as COVID-19-associated coagulopathy (CAC) and endothelial-derived vWF may play a significant role in it." (PMID 36982738, 2023). "However, as VWF is also an acute-phase protein, whether it is a bystander or a relevant factor in the pathogenesis of COVID-19 should be carefully evaluated." (PMID 37333991, 2023). "Different mechanisms have been implicated in the pathogenesis of SVT thrombosis in COVID-19 patients, including: high release of proinflammatory cytokines, endothelial direct damage by the virus, increased procoagulant factors (notably VIII-F, vWF and V-F) and NETs." (PMID 36768584, 2023). "ABO(H) glycans on the viral S protein or lung epithelial cells may impact viral infection, while ABO(H) antigens on von Willebrand factor (vWF) and coagulation factor VIII (FVIII) are known to impact thromboembolic risk, which may impact COVID-19 disease severity." (PMID 36696414, 2023). "Organ failure is worse in advanced COVID-19 patients, so vascular endothelial cell injury markers such as soluble thrombomodulin (sTM), VWF and PAI-I are high, while AT levels are low, suggesting that hypofibrinolysis may be related to organ failure and vascular endothelial cell injury." (PMID 37175680, 2023). "Thus, a dysregulation of ADAMTS-13 in COVID-19 could lead to increased VWF activity, thereby fostering the microvascular thrombosis." (PMID 38077924, 2023). "As both vWF and ADAMTS13 have been shown to play a crucial role in the development of thromboembolism in COVID-19, we aimed to explore whether their missense variants might be correlated with progression scores of the disease by directly modulating the prothrombotic activity of these proteins." (PMID 36980889, 2023). "Binary regression analysis showed that elevated selectins P, E and L and VWF in COVID-19 patients at the time of hospital admission could predict future thrombosis; in contrast to TLC, NLR, lymphocytes percentage, platelets count, CRP, LDH, IL-6 and PCT that could not." (PMID 35061142, 2022). "Therefore, a potential target in the thrombophylactic treatment of COVID-19, could be the modulation of endothelial cell activation, in particular related to VWF and ADAMTS-13." (PMID 35482749, 2022). "In patients with COVID-19, the level of von Willebrand factor, which is a circulating adhesive glycoprotein secreted by ECs, is considerably elevated, directing both endothelial infection with SARS-CoV-2 and the indirect damage caused by inflammation in COVID-19-associated coagulopathy." (PMID 35240982, 2022).